SURF4 (surfeit 4)
Description:
Endoplasmic reticulum cargo receptor that mediates the export of lipoproteins by recruiting cargos into COPII vesicles to facilitate their secretion. Acts as a cargo receptor for lipoproteins bearing both APOB and APOA1, thereby regulating lipoprotein delivery and the maintenance of lipid homeostasis. Synergizes with the GTPase SAR1B to mediate transport of circulating lipoproteins. Promotes the secretion of PCSK9. Also mediates the efficient secretion of erythropoietin (EPO). May also play a role in the maintenance of the architecture of the endoplasmic reticulum-Golgi intermediate compartment and of the Golgi.
Synonyms: ERV29; FLJ22993; MGC102753
Tractability: Antibody: its Gene Ontology location is reachable by antibodies, with high confidence; UniProt predicts a signal peptide or a membrane-spanning region. PROTAC: ubiquitination databases record sites on it; its protein half-life has been measured.
Gene: Protein-coding gene on chromosome 9 (133,361,450 to 133,376,166, reverse strand). Ensembl gene ENSG00000148248.
Subcellular location: Endoplasmic reticulum membrane; Endoplasmic reticulum-Golgi intermediate compartment membrane; Golgi apparatus membrane
Subcellular location (Human Protein Atlas): Endoplasmic reticulum; Golgi apparatus; Nuclear membrane; Cytosol
Pathways (Reactome):
Immune System: Neutrophil degranulation
Vesicle-mediated transport: COPI-dependent Golgi-to-ER retrograde traffic
Gene Ontology:
Molecular function: cargo receptor activity; COPII receptor activity; protein binding
Biological process: early endosome to Golgi transport; Golgi organization; lipid homeostasis; lipoprotein transport; regulation of lipid transport; COPII-coated vesicle cargo loading; endoplasmic reticulum to Golgi vesicle-mediated transport; lipid export from cell
Cellular component: COPII-coated ER to Golgi transport vesicle; endoplasmic reticulum; endoplasmic reticulum exit site; endoplasmic reticulum membrane; endoplasmic reticulum-Golgi intermediate compartment; endoplasmic reticulum-Golgi intermediate compartment membrane; Golgi apparatus; Golgi membrane; azurophil granule membrane; plasma membrane; transport vesicle; membrane
Genetic constraint (gnomAD): Loss-of-function variants: 3 observed, 29.16 expected, observed/expected ratio (o/e) 0.1, 90% interval 0.046 to 0.27. The upper end of that interval is the gene's LOEUF score, 0.27, which puts it in group 1 of 6, group 1 being the genes least tolerant of losing a copy. Missense variants: 217 observed, 354.28 expected, observed/expected ratio (o/e) 0.61, 90% interval 0.55 to 0.69. Synonymous variants: 143 observed, 140.23 expected, observed/expected ratio (o/e) 1.02, 90% interval 0.89 to 1.17.
Homologues: Orthologues: macaque SURF4 (99% identical), mouse Surf4 (99% identical), rat Surf1 (99% identical), guinea pig SURF4 (99% identical), dog SURF4 (97% identical), chimpanzee SURF4 (96% identical), pig SURF4 (95% identical), tropical clawed frog surf4.2 (91% identical), zebrafish surf4 (88% identical), zebrafish surf4l (87% identical), Drosophila melanogaster Surf4 (59% identical), Caenorhabditis elegans sft-4 (58% identical). Paralogues in human: SURF1 (17% identical).
Diseases named in the same sentence as SURF4 in open-access papers:
SURF4 is named in the same sentence as 44 diseases in open-access papers, as found by Europe PMC text mining. Sharing a sentence is not in itself a finding about the gene and the disease. The quoted sentences say what the papers report.
atherosclerosis (6 papers, 2021 to 2024). A disease characterized by the build-up of fatty material and calcium deposition in the arterial wall resulting in partial or complete occlusion of the arterial lumen. "In different mouse models, silencing of hepatic Surf4 dramatically reduces plasma lipid levels and the development of atherosclerosis without causing overt liver damage." (PMID 39105051, 2024). "Thus, our findings indicate that Surf4-based therapy can potentially lower plasma LDL-C levels by inhibiting VLDL secretion and subsequent LDL production, thereby reducing the risk of atherosclerosis for patients who are intolerant to or cannot be effectively managed by existing therapies." (PMID 34118252, 2021). "Consistently, they reported that knockout of hepatic Surf4 using CRISPR-Cas9 significantly reduced plasma levels of cholesterol and TGs and reduced the development of atherosclerosis in a mouse model of hypercholesterolemia induced by overexpressing PCSK9." (PMID 34118252, 2021). "Deficiency of hepatic Surf4 significantly reduces VLDL secretion, plasma cholesterol levels and the development of atherosclerosis but does not cause notable liver damage or hepatic lipid accumulation in mice." (PMID 34859075, 2021). "Inhibition of hepatic Surf4 reduced VLDL secretion and the development of atherosclerosis." (PMID 34118252, 2021). "In summary, hepatic deficiency of Surf4 reduced VLDL secretion and the development of atherosclerosis but did not cause significant hepatic lipid accumulation or liver damage." (PMID 34118252, 2021). "Although liver cholesterol and TG levels were elevated in mice with complete deficiency of SURF4, significant protection against pathological dyslipidemia and atherosclerosis was observed in heterozygotes for Surf4 knockout without any observable hepatic damage." (PMID 38216994, 2024).
ovarian carcinoma (4 papers, 2022 to 2025). A malignant neoplasm originating from the surface ovarian epithelium. "In tumors, SURF4 reportedly promotes tumorigenesis in breast cancer, ovarian cancer, and myeloid leukemia." (PMID 38526631, 2024). "Surf4 expression is also upregulated in ovarian cancer stem cells, and knockdown of Surf4 inhibits tumorigenesis." (PMID 36574593, 2023).
breast carcinoma (3 papers, 2022 to 2024). "The receiver operating characteristic (ROC) curves were plotted to evaluate the diagnostic value of SURF4 expression for breast cancer." (PMID 36446386, 2022). "High expression of SURF4 was also observed in breast cancer tissue and cells, with SURF4 promoting the proliferation and migration of breast cancer cells and being associated with poor prognosis." (PMID 37644433, 2023). "The age, stage, and SURF4 expression exhibited independent prognostic value for OS of breast cancer." (PMID 36446386, 2022). "The high SURF4 expression in breast cancer tissue was further validated by immunohistochemistry (IHC)." (PMID 36446386, 2022). "Significant high SURF4 expression (P < 0.01) was observed in MCF7 (Human luminal A type breast cancer cell), BT474 (Human luminal B type breast cancer cell), SKBR3 (Human HER2 overexpression type breast cancer cell), MDAMB231 and 4T1 (Human triple-negative breast cancer cell)." (PMID 36446386, 2022). "The high SURF4 expression in breast cancer tissue was further validated by IHC." (PMID 36446386, 2022). "High SURF4 expression was observed in breast cancer tissue and cell." (PMID 36446386, 2022). "In this study, high expression of SURF4 was first found in breast cancer." (PMID 36446386, 2022). "High SURF4 expression was confirmed in breast cancer tissue and cells." (PMID 36446386, 2022). "The results showed that SURF4 may influence the development of breast cancer by controlling chemokine signaling pathway, Th17 cell differentiation, primary immunodeficiency, etc." (PMID 36446386, 2022). "The age [hazard ratio (HR): 2.317, 95% confidence interval (CI): 1.452-3.699, P < 0.001], stage (HR: 2.090, 95% CI: 1.585-2.755, P < 0.001), and SURF4 expression (HR: 1.958, 95% CI: 1.230-3.115, P = 0.005) exhibited independent prognostic value for OS of breast cancer." (PMID 36446386, 2022). "Besides, SURF4 is significantly (P < 0.001) highly expressed in breast cancer in comparison with paired normal breast tissue." (PMID 36446386, 2022). "In conclusion, high expression of SURF4 was first found in breast cancer." (PMID 36446386, 2022). "Moreover, high SURF4 expression was correlated with poor RFS of breast cancer patients in infiltrating ductal carcinoma (P = 0.018), ER negative (P = 0.019), PR negative (P = 0.008) by subgroup analysis." (PMID 36446386, 2022). "Our study reported a novel biomarker SURF4 in breast cancer." (PMID 36446386, 2022). "SURF4 may be a biomarker to play a role in diagnosis and prognosis of breast cancer." (PMID 36446386, 2022). "Besides, significant high SURF4 expression (P < 0.01) was observed in MCF7 (Human luminal A type breast cancer cell), BT474 (Human luminal B type breast cancer cell), SKBR3 (Human HER2 overexpression type breast cancer cell), MDAMB231 and 4T1 (Human triple-negative breast cancer cell)." (PMID 36446386, 2022). "Our findings may indicate SURF4 as a novel therapeutic target for treatment of breast cancer." (PMID 36446386, 2022). "SURF4 may be a biomarker in diagnosis and prognosis of breast cancer." (PMID 36446386, 2022). "However, the role of SURF4 in breast cancer has not been demonstrated yet." (PMID 36446386, 2022).
dyslipidaemia (2 papers, 2023 to 2025). "Our study provides novel insights into the role of PCOS in dyslipidaemia, with intestinal SURF4 potentially playing a key regulatory role in lipid metabolism." (PMID 41041130, 2025). "The PCOS rat model exhibited significant upregulation of intestinal SURF4 accompanied by dyslipidaemia and elevated androgen levels." (PMID 41041130, 2025). "Our findings indicate that the characteristic hyperandrogenism and metabolic dysfunction in PCOS may lead to elevated lipid levels through the upregulation of intestinal SURF4, underscoring its potential as a regulatory factor in the pathogenesis of PCOS-associated dyslipidaemia." (PMID 41041130, 2025). "Here, we reviewed the physiological functions of Surf4, with particular emphasis on recent advances in the role of Surf4 in lipid metabolism, which may pave the way for the development of potential novel clinical interventions for dyslipidaemia and other related human diseases." (PMID 36574593, 2023).
fatty liver (2 papers, 2024). "However, we cannot exclude the possibility that accumulated SAA1 in Surf4-deficient hepatocytes is involved in the development of the mild fatty liver." (PMID 39105051, 2024). "Inhibiting SURF4 to decrease VLDL secretion and circulating lipids has been shown to be dose dependent and safe, suggesting that it has the potential to lower plasma lipids without inducing hepatic steatosis." (PMID 38216994, 2024).
hepatocellular carcinoma (2 papers, 2019 to 2021). A malignant tumor that arises from hepatocytes. "To test this hypothesis, we knocked down the expression of Surf4 in human hepatoma-derived cell lines, Huh7 and HepG2 that express and secrete both apoB and apoA-I." (PMID 34118252, 2021). "In contrast, we found that Surf4 was not required for endogenous PCSK9 secretion from cultured human hepatoma-derived cell lines, Huh7 and HepG2 cells." (PMID 34118252, 2021).
Hypercholesterolemia (2 papers, 2018 to 2021). An increased concentration of cholesterol in the blood. "Taken together with the marked reductions in plasma cholesterol associated with genetic or therapy-induced reductions in plasma PCSK9, our findings raise the possibility that SURF4 could represent an additional novel therapeutic target for the treatment of hypercholesterolemia." (PMID 30251625, 2018).
liver fibrosis (2 papers, 2023 to 2024). "Hepatic Surf4 deficiency significantly decreased SAA1 secretion from isolated primary hepatocytes, lowered circulating SAA1 levels, and attenuated liver fibrosis in mice receiving CCl4." (PMID 39105051, 2024). "Nevertheless, knockout of hepatic Surf4 reduces collagen content and inflammation in the liver of mice receiving CCl4, thereby attenuating liver fibrosis." (PMID 39105051, 2024). "Therefore, to understand how knockout of hepatic Surf4 affected CCl4-induced liver fibrosis, we evaluated expression of lecithin:retinol acyltransferase (LRAT), an HSC cell marker, and α-SMA, a marker for HSC activation." (PMID 39105051, 2024). "Here, we observed that hepatic Surf4 deficiency has a similar effect on plasma lipids and liver fibrosis in male and female mice administered CCl4, implying no notable impact of sex differences." (PMID 39105051, 2024). "Therefore, we investigated the possibility that Surf4-deficient hepatocytes impaired SAA1 secretion and consequently reduced HSC activation and liver fibrosis." (PMID 39105051, 2024). "Furthermore, SAA1 knockdown, like hepatic Surf4 deficiency, substantially reduces liver fibrosis in Surf4flox mice, but has no detectable effect on liver fibrosis in Surf4LKO mice, suggesting the contribution of SAA1 to Surf4 deficiency-induced alleviation of liver fibrosis in mice." (PMID 39105051, 2024). "Therefore, this study aims to investigate whether and how hepatic Surf4 affects liver fibrosis." (PMID 39105051, 2024). "To understand how knockout of Surf4 in hepatocytes affected HSC activation and liver fibrosis, we performed proteomics on plasma samples and identified 932 proteins (57 up-regulated and 190 down-regulated) in Surf4LKO mice compared with Surf4flox mice." (PMID 39105051, 2024). "Lack of Surf4 also significantly reduced the expression of liver fibrosis markers (Col1a, Acta2/α-Sma) and inflammation markers (Il-1β and Tnf-α) at mRNA and protein levels in male and female Surf4LKO mice." (PMID 39105051, 2024). "Therefore, Surf4 mediates hepatic SAA1 secretion, which activates HSCs and exacerbates liver fibrosis." (PMID 39105051, 2024). "Altogether, these data suggest that Surf4 mediates SAA1 secretion, which may activate HSCs in a paracrine manner via TLR2, thus exacerbating liver fibrosis." (PMID 39105051, 2024). "Therefore, hepatic Surf4 facilitates SAA1 secretion, activates HSCs, and aggravates liver fibrosis, suggesting that hepatic Surf4 and SAA1 may serve as treatment targets for liver fibrosis." (PMID 39105051, 2024).
bladder urothelial carcinoma (1 paper, 2022). "Significant high SURF4 expression was found in bladder urothelial carcinoma, etc." (PMID 36446386, 2022).
COPA syndrome (1 paper, 2022). "This phenotype was ablated in cGAS−/−/SURF4−/− THP-1 cells (preliminary data) further supporting the requirement of cGAS as the initial driver for STING accumulation at the Golgi and subsequent inflammatory signalling in COPA syndrome." (PMID 35484149, 2022).
diabetes (1 paper, 2022). "This implies that the loss-of-function of Surf4 in β cells might increase the risk for the onset and progression of diabetes." (PMID 35562580, 2022).
hepatoblastoma (1 paper, 2024). Hepatoblastoma (HB) is a malignant hepatic tumor and is the most common pediatric liver cancer. "We also silenced Surf4 in the cultured human hepatoblastoma-derived cell line, HepG2." (PMID 39105051, 2024).
hyperandrogenism (1 paper, 2025). Excessive secretion of androgens from the adrenal glands or gonads. "Future research should focus on elucidating the molecular mechanisms linking hyperandrogenism, intestinal SURF4, and lipid metabolism using advanced in vivo and in vitro models." (PMID 41041130, 2025). "Similarly, our study demonstrated a sex-specific pattern of intestinal SURF4 expression, showing varying degrees of upregulation in female PCOS rats with hyperandrogenism induced by both endogenous and exogenous sources." (PMID 41041130, 2025).
hyperlipidemia (1 paper, 2025). "Given the established positive correlation between elevated serum PCSK9 levels, SURF4 upregulation, and hyperlipidemia—particularly through SURF4-mediated hepatic lipoprotein packaging and subsequent metabolic inactivation—we measured serum PCSK9 levels." (PMID 41041130, 2025).
Hypocholesterolemia (1 paper, 2022). An decreased concentration of cholesterol in the blood. "We found that embryonic deletion of Surf4 in hepatocytes results in profound hypocholesterolemia in mice associated with impaired hepatic lipoprotein secretion and normal dietary fat absorption." (PMID 36193893, 2022). "A role for SURF4 in APOB secretion was further supported by a recent study in which acute deletion of hepatic Surf4 in adult mice caused hypocholesterolemia and a reduction in hepatic lipoprotein secretion." (PMID 36193893, 2022). "The profound hypocholesterolemia we observed in Surf4fl/fl Alb-Cre+ mice is in agreement with two other studies in which hepatic Surf4 was acutely inactivated using an AAV/Cas9 mouse system or a similar Surf4fl/fl and Alb-Cre model." (PMID 36193893, 2022). "To confirm the profound hypocholesterolemia with few adverse consequences observed in Surf4fl/fl Alb-Cre+ mice, and to further explore SURF4 inhibition as a potential therapeutic approach, we next tested depletion of hepatic SURF4 using liver-targeted siRNA in adult mice." (PMID 36193893, 2022). "Deletion of hepatic Surf4 results in decreased serum PCSK9 level and profound hypocholesterolemia in mice." (PMID 36193893, 2022).
infiltrating ductal carcinoma (1 paper, 2022). "High expression of SURF4 was observed in T4, infiltrating ductal carcinoma, ER negative, PR negative, and HER2 positive, female, patients without lymph node metastasis, HER2 overexpression type, and deceased patients." (PMID 36446386, 2022). "High expression of SURF4 was observed in T4, infiltrating ductal carcinoma, ER negative, PR negative, HER2 positive, female, patients without lymph node metastasis, HER2 overexpression type, and deceased patients." (PMID 36446386, 2022). "The expression of SURF4 was highest in T4 (P = 0.014), infiltrating ductal carcinoma (P < 0.001), ER negative (P < 0.001), PR negative (P < 0.001), and HER2 positive (P < 0.001) patients." (PMID 36446386, 2022).
insulinoma (1 paper, 2022). "We first examined the expression of Surf4 in human HAP1 cells and rat insulinoma INS-1 832/13 cells." (PMID 35562580, 2022). "Under high-glucose conditions, Surf4 expression was upregulated, and Surf4 proteins mainly localized to the ER at a steady state and accumulated in the ERES, along with proinsulin in rat insulinoma INS-1 cells." (PMID 35562580, 2022).
lipid metabolic disorders (1 paper, 2025). "The upregulation of intestinal SURF4 in PCOS and its potential regulation by elevated androgen levels highlights a significant target for addressing lipid metabolic disorders associated with PCOS." (PMID 41041130, 2025).